TET2 (tet methylcytosine dioxygenase 2)
Diseases named in the same sentence as TET2 in open-access papers (continued):
Sharing a sentence is not in itself a finding about the gene and the disease.
Obesity (continued). "Overall, these results show that conditional Tet2 deletion in adipocytes protects against HFD-induced obesity and insulin resistance, mainly ascribed to an increase in energy consumption and a reduction in food intake." (PMID 38561362, 2024). "Here, we find that obesity decreases DNA hydroxymethylation and TET2 levels in adipocytes via the leptin signaling pathway." (PMID 38561362, 2024). "In this study, we demonstrate that obesity leads to a decrease in 5-hmC and TET2 levels in adipocytes, which was primarily attributed to hyperleptinemia." (PMID 38561362, 2024). "To explain the temporal discrepancy in the reduction of adipocyte Tet2 levels in iWAT and eWAT during obesity, we investigated the leptin levels in these two types of adipocytes." (PMID 38561362, 2024). "Previous research into the role of TET2 in metabolic dysfunction revealed that reduced Tet2 expression in adipose tissue endothelial cells promotes obesity by impeding vascularization and suppressing the browning of white adipose tissue." (PMID 39872508, 2024). "Overall, obesity-induced downregulation of adipocyte TET2 is primarily attributed to hyperleptinemia." (PMID 38561362, 2024). "We next focused our efforts on understanding the mechanism or mechanisms by which obesity drives CH in HSC/Ps bearing CHIP mutations and used the Tet2-mutant model to study this." (PMID 37071471, 2023). "In this study, we evaluated the expression levels of TET2 and 5-hmC in obesity-related CRC and the effects of TET2 expression on the proliferative activity in CRC cells." (PMID 36806702, 2023). "In this study, we aimed to evaluate the expression levels of TET2 and 5-hmC in obesity-related CRC and the effects of TET2 expression on the proliferation of CRC cells." (PMID 36806702, 2023). "Recent studies have demonstrated that TET2 acts as a DNA demethylase to regulate gene expression in human and mouse endothelial cells, and these studies have indicated that endothelial TET2 deficiency exacerbates HFD-induced obesity." (PMID 40620794, 2025). "Therefore, it appears that the reduced sensitivity to leptin, rather than leptin concentration, contributes to the delayed decline of adipocyte Tet2 levels in eWAT during obesity." (PMID 38561362, 2024). "In light of this understanding and given that Tet2 expression is downregulated in obesity, one would intuitively hypothesize that adipose deletion of Tet2 would exacerbate diet-induced obesity." (PMID 39872508, 2024). "Consistently, in the leptin-deficient (ob/ob) obese mice, adipocyte expression of TET2 were elevated when compared with lean controls, suggesting that leptin, rather than obesity, negatively regulated the expression of TET2 in adipocytes." (PMID 38561362, 2024). "Our findings support the existence of a negative feedback loop between TET2 and leptin in adipocytes and reveal a compensatory mechanism for the body to counteract the metabolic dysfunction caused by obesity." (PMID 38561362, 2024). "Our study demonstrated that loss of Tet2 in adipocytes led to the reduction of circulating leptin levels and a marked increase in basal and leptin-induced p-STAT3 levels in the hypothalamus, accompanied by resistance to HFD-induced obesity." (PMID 38561362, 2024). "Furthermore, we identify the crucial role of adipocyte TET2 in HFD-induced obesity and elucidate that TET2 interacts with transcription factor C/EBPα to control leptin gene expression, thereby regulating body weight." (PMID 38561362, 2024). "A final question arises about the capacity of TET2 modulation to treat obesity." (PMID 39872508, 2024). "To investigate the relationship between CHIP and obesity, we analyzed several mouse models harboring common CHIP mutations: Tet2, Dnmt3a, Asxl1, or Jak2 on the background of LepOb/Ob (Ob/Ob) mice to mimic the human pre-LHSCs/PCs condition occurring in individuals with obesity." (PMID 37071471, 2023).
Obesity (continued). "Therefore, we also examined the role of SOCE inhibitors in suppressing Tet2-mediated clonal expansion under conditions of obesity." (PMID 37071471, 2023). "The mechanism underlying why only TET2, among the TET family members, is susceptible to obesity and metabolic alterations in CRC remains unclear." (PMID 36806702, 2023). "Downregulation of TET2 may promote the development of obesity-related CRC by inhibiting the protective effect of 5-hmC on DNA damage." (PMID 36806702, 2023). "We believe that the reduction of 5-hmC associated with decreased TET2 expression and nuclear localization of TET2 may influence the development of obesity-related CRC." (PMID 36806702, 2023). "TET2-mediated epigenetic modifications, influenced by systemic metabolic alterations, are proposed as a novel developmental mechanism in obesity-related CRC, and therefore, may be a promising therapeutic target." (PMID 36806702, 2023). "However, the regulation and function of TET2 in adipocytes during obesity are poorly understood." (PMID 38561362, 2024). "Although the decrease in TET2 expression in adipocytes did not prevent the increase in leptin levels during obesity, the loss of Tet2 in obese mice resulted in the downregulation of leptin levels and an enhancement of leptin sensitivity, which ultimately led to weight loss." (PMID 38561362, 2024). "Additionally, obesity-induced decline of adipocyte Tet2 levels is much later in eWAT than in iWAT." (PMID 38561362, 2024). "Regulating TET2 might lead to the amelioration of obesity-related pathological conditions." (PMID 36806702, 2023). "In addition to its role in the adipose tissue, TET2 may be involved in obesity-related CRC development." (PMID 36806702, 2023). "Furthermore, in 2007, the FTO (fat mass and obesity associated) gene was found to encode a functional homologue of AlkB, and two more genes, TET1 and TET2, suggested possibility as a similar mechanism." (PMID 21285982, 2011). "Deleting all three TET enzymes (TET1, TET2, and TET3) in fat cells protects against obesity during a dietary challenge by enhancing β-adrenergic-induced lipolysis and increasing adipose tissue thermogenesis." (PMID 39872508, 2024). "Mouse models of obesity and CHIP driven by heterozygosity of Tet2, Dnmt3a, Asxl1, and Jak2 resulted in exacerbated expansion of mutant HSC/Ps due in part to excessive inflammation." (PMID 37071471, 2023). "In mice, TET2-driven CHIP leads to an increased expression of IL-1ß in white adipose tissue, exacerbating age- and obesity-related insulin-resistance and hyperglycemia." (PMID 38162500, 2023). "In this study, we observed that TET2 and 5-hmC expression was reduced in patients with CRC with visceral fat obesity, insulin resistance, and hyperglycemia." (PMID 36806702, 2023). "Moreover, we observed higher expression levels in SAT compared to OVAT for the erasers TET1, TET2, and TET3, while the expression is lower across tissue depots among subjects with obesity." (PMID 41030849, 2025). "These human data indicate that obesity-related hyperleptinemia is associated with a decline in TET2 expression in adipocytes, supporting a negative feedback loop between TET2 and leptin in the context of obesity." (PMID 38561362, 2024). "This study did not clarify the effects of 5-hmC levels, obesity, and metabolic factors on the expression of TET2 and AMPK in CRC." (PMID 36806702, 2023). "Furthermore, analysis of human data provided evidence for a negative feedback loop between TET2 and leptin in the context of obesity." (PMID 40620794, 2025). "Here, the authors demonstrate a negative feedback loop between TET2, a DNA demethylation enzyme, and leptin, an adipokine, in adipocytes, unveiling a compensatory mechanism by which the body counteracts the metabolic dysfunction induced by obesity." (PMID 38561362, 2024). "Therefore, in obesity-related CRC, hyperinsulinemia and hyperglycemia may be involved in the decreased expression of TET2 by an AMPK-mediated mechanism." (PMID 36806702, 2023).
Autoimmunity (16 papers, 2016 to 2025). The occurrence of an immune reaction against the organism's own cells or tissues. "Mice with B‐cell‐specific Tet2 knockout appeared to experience a minor effect in B‐cell development, but together with Tet3 deficiency it caused spontaneous hyperactivation of both B and T cells and autoimmunity." (PMID 39722652, 2025). "Co-segregation of autoimmunity and impaired T-cell apoptosis may suggest the pathogenic role of an apoptosis defect in development of manifest autoimmunity in patients with TET2 loss-of-function." (PMID 36870198, 2023). "Importantly, the increased Foxp3 CNS2 DNA methylation in NOD mice <30 days of age with a very early onset of autoimmunity suggests a potential causative role of miR142-3p/Tet2 signaling in promoting autoimmune activation and progression." (PMID 31836704, 2019). "From an immunopathological perspective, the analysis of murine and human T cell samples with recent onset of autoimmunity/T1D directly links Tet2 abundance and the methylation status of the Foxp3 CNS2 with islet autoimmunity in vivo." (PMID 31836704, 2019). "As Tregs from Tet deficient mice displayed abnormal proliferation along with FOXP3 destabilization, Treg dysfunction may represent an additional mechanism of autoimmunity in patients with TET2 defect." (PMID 36870198, 2023). "Soon after weaning, at 3–4 weeks, a period of time that has been associated with the initiation of autoimmunity, we found a modest increase in expression of Tet1 but substantially increased expression of Tet2 in whole islets in NOD mice but not immune-deficient NOD/scid mice of the same age." (PMID 34417463, 2021). "However, recent reports of PNH arising in the setting of a CALR-mutated MPN,CML and a relapse of AML associated with TET2 and JAK2 mutations raise the question of whether autoimmunity is necessary in all cases." (PMID 31453016, 2019). "All PRKCD, CTLA4, TET2 and NRAS/KRAS patients presented clinically with lymphoproliferation and autoimmunity, considering all those reported cases (n=197) as ALPS-like patients." (PMID 34447369, 2021). "A series of studies have demonstrated that Tet2/Tet3 DKO in B cells is a key factor that contributes to the spontaneous hyperactivation of both B and T cells, autoantibody production and autoimmunity development." (PMID 34222235, 2021). "Defective TET2 expression might affect the recruitment of IFN‐γ‐secreted CD8+ T cells and Thq cells, leading to severe autoimmunity." (PMID 40599235, 2025). "Animal studies suggest that Tet2- and Tet3-mediated chromatin modification participated in the repression of CD86 on self-reactive B cells, a mechanism that may contribute to autoimmunity prevention." (PMID 37048133, 2023). "Additionally, given that CD86 overexpression in tolerant B cells caused them to break tolerance, collectively, Tet2 and Tet3 are essential for CD86 expression suppression in self-tolerant B cells and play important roles in autoimmunity prevention." (PMID 34222235, 2021). "However, only 100% of CTLA4, PRKCD, TET2 and NRAS/KRAS reported patients had an ALPS-like presentation, while the autoimmunity and lymphoproliferation combination resulted rare in other genetic defects." (PMID 34447369, 2021). "The thylcytosine dioxygenase TET2 could promote DNA demethylation to control the production of IFN-γ and IL-17 in autoimmunity, and was required to resolve inflammation by recruiting HDAC2 and repressing transcription of IL-6 through histone deacetylation." (PMID 28915632, 2017).
chronic lymphocytic leukemia (15 papers, 2014 to 2025). "Epigenetic changes mediated by loss of function of TET methylcytosine dioxygenase 2 (TET2) have been observed in CD19-targeted CAR-T cells in patients with chronic lymphocytic leukemia." (PMID 37781382, 2023). "TET2 expression and mutations have been less studied in chronic lymphocytic leukemia (CLL) and only rare cases of this disease showed TET2 mutations." (PMID 24693539, 2014). "In a landmark case of chronic lymphocytic leukemia (CLL), lentiviral integration of the CAR transgene disrupted the TET2 gene in one T cell, creating a hypomorphic loss-of-function state." (PMID 41280924, 2025). "Tet2 null mice develop many hematopoietic abnormalities with myeloid proliferative neoplasms and chronic lymphocytic leukemia, hinting that Tet2 is also a tumor suppressor in hematopoietic tissue." (PMID 38028538, 2023). "A chronic lymphocytic leukemia patient in a clinical trial for CD19 CAR T cell therapy (trial: NCT01029366) exhibited clonal CAR T cell expansion due to retroviral insertion disrupting the TET2 gene." (PMID 41117994, 2025). "Moreover, the role of TET2 in chronic lymphocytic leukemia (CLL) is unknown." (PMID 24693539, 2014).
colitis (15 papers, 2017 to 2025). Inflammation of the colon. "TET2 inactivation has been considered to underlie the proinflammatory milieu, as Tet2 knockout mice are susceptible to DSS-induced colitis with hyperactivation of Il6 during inflammation." (PMID 38822028, 2024). "Interestingly, Tet2-deficient primary mice appear to develop colitis spontaneously as shown by fluorescein 5-isothiocyanate staining in the serum and hematoxylin-eosin staining in the colon." (PMID 40230417, 2025). "Consistently, even low-dose DSS feeding induced exacerbated colitis in Tet2-deficient primary mice." (PMID 40230417, 2025). "Notably, recent work has implicated TET2/3 as critical mediators of the response of mice to chemically induced colitis by regulation of POU2F3-methylation and SI tuft cell abundance, further supporting the importance of this cell-type in governing immune response in gut." (PMID 39609081, 2025). "In summary, the present study demonstrates that the gut-bone marrow axis plays an important role in the co-symptoms of colitis and leukemia in the Tet2-mutant chimeric and primary mice." (PMID 40230417, 2025). "For example, our previous study showed that the epigenetic modifier Tet2 associates Hdac2 to repress IL-6 during inflammation resolution in myeloid cells, which restrains DSS-induced colitis in mice." (PMID 38346956, 2024). "On day 3, colitis mice were treated with Tet1/Tet2 siRNA-treated PDLSCs or control PDLSCs by systemic transplantation through tail vein, followed by sacrifice of the mice on day 10 to collect samples for evaluation." (PMID 31611558, 2019). "Tet1 and Tet2 deficiency enhances PDLSC-induced T cell apoptosis and ameliorates the disease phenotype in colitis mice." (PMID 31611558, 2019). "To further assess the role of Tet1 and Tet2 in immunomodulation by PDLSCs, we compared the immunotherapeutic effects of control and Tet1/Tet2 siRNA-treated PDLSCs in experimental colitis mice." (PMID 31611558, 2019). "Tet1 and Tet2 deficiency enhance PDLSC-induced T cell apoptosis and ameliorate the disease phenotype in colitis mice." (PMID 31611558, 2019). "TET2 represses late-phase expression of dendritic cell pro-inflammatory molecules such as IL-6, MCP-1 and MCP-3 in response to LPS stimulation and TET2 knockout results in a greater degree of inflammatory response in mice challenged with LPS and colitis." (PMID 30301842, 2018). "Importantly, when PDLSCs were systematically infused into DSS-induced colitis mice, Tet1/Tet2-downregulated PDLSCs showed significantly increased therapeutic effects." (PMID 31611558, 2019). "Tet2-deficient macrophages and dendritic cells produce more IL-6 in response to stimulation, rendering Tet2-deficient mice more susceptible than WT mice to endotoxin-induced shock and DSS-induced colitis." (PMID 28408905, 2017).
diffuse large B-cell lymphoma (15 papers, 2019 to 2025). "Remarkably, in a cohort of 128 patients with diffuse large B-cell lymphomas, TET2 loss of function mutations was found in ∼12% of the cases." (PMID 35386689, 2022). "TET2 is frequently mutated in diffuse large B-cell lymphoma (DLBCL)." (PMID 33520997, 2020). "Furthermore, TET2 is one of the most frequently mutated genes (6–12%) in diffuse large B cell lymphoma, a malignancy originating from germinal center B cells." (PMID 30809228, 2019). "TET2 mutations are also frequent in B-cell malignancies, particularly in diffuse large B-cell lymphoma (DLBCL; 6~12%), the most common type of non-Hodgkin’s lymphoma arising from germinal center B cells." (PMID 36675240, 2023). "TET2 deficiency in diffuse large B-cell lymphoma (DLBCL) leads to hypermethylation in germinal center B-cells and links to transcriptional repression of antigen presentation genes or interferon pathway genes via promoter hypermethylation and loss of enhancer 5hmC." (PMID 38914477, 2024). "In various B cell lymphomas, such as diffuse large B cell lymphoma (DLBCL) or follicular lymphoma (FL), somatic mutations in KMT2D (MLL2), EZH2, CREBBP, and TET2 are frequent events, affecting germinal center (GC) formation and affinity maturation." (PMID 37648814, 2023). "Diffuse large B cell lymphomas underexpress TET2 relative to control lymphocytes, and it has recently been shown that TET2 deficiency promotes lymphomagenesis, underscoring the rationale to enhance activity of this tumor-suppressor gene." (PMID 31911474, 2020). "Enzymes of the TET family and especially TET2 and TET3 regulate enhancer activity and DNA methylation dynamics during B cell development, while TET2 mutations or defects are frequent in hematological malignancies such as diffuse large B cell lymphoma." (PMID 36770824, 2023). "However, in diffuse large B‐cell lymphoma (DLBCL), Tanager and colleagues confirmed that although most tumors showed a reduction in 5hmC, only approximately half harboured mutations in epigenetic regulators such as TET2 and DNMT3A." (PMID 40116537, 2025). "Notably, AID facilitates TET2-mediated demethylation of the FANCA gene as a transcriptional cofactor in diffuse large B-cell lymphoma (DLBCL), while paradoxically collaborating with DNMT1 to maintain methylation at the BCL6 promoter." (PMID 40270606, 2025). "In diffuse large B-cell lymphoma (DLBCL) cell lines, AID cooperates with the TET enzyme TET2 to demethylate Fanconi anemia complementation group A (FANCA), increasing its expression." (PMID 39280246, 2024). "Furthermore, the TET2/AID complex, which bound to the FA complementation group A (FANCA) promoter and induced its hypomethylation, facilitated oncogenic FANCA in diffuse large B cell lymphoma." (PMID 33029541, 2020).